NACC1 (nucleus accumbens associated 1)
Description:
Functions as a transcriptional repressor. Seems to function as a transcriptional corepressor in neuronal cells through recruitment of HDAC3 and HDAC4. Contributes to tumor progression, and tumor cell proliferation and survival. This may be mediated at least in part through repressing transcriptional activity of GADD45GIP1. Required for recruiting the proteasome from the nucleus to the cytoplasm and dendritic spines.
Synonyms: NAC-1; BTBD14B; NAC1; BEND8; BTBD30; NECFM
Tractability: PROTAC: UniProt records ubiquitination sites on it; ubiquitination databases record sites on it; its protein half-life has been measured.
Gene: Protein-coding gene on chromosome 19 (13,116,468 to 13,141,147, forward strand). Ensembl gene ENSG00000160877.
Subcellular location: Nucleus; Cytoplasm
Subcellular location (Human Protein Atlas): Nucleoplasm; Cytosol; Vesicles
Gene Ontology:
Molecular function: protein binding; DNA-binding transcription factor activity, RNA polymerase II-specific; DNA-binding transcription repressor activity, RNA polymerase II-specific; histone deacetylase binding; RNA polymerase II cis-regulatory region sequence-specific DNA binding; DNA binding
Biological process: negative regulation of DNA-templated transcription; positive regulation of cell population proliferation; regulation of transcription by RNA polymerase II; negative regulation of transcription by RNA polymerase II; regulation of cell population proliferation
Cellular component: cytosol; nucleoplasm; nucleus; cytoplasm
Genetic constraint (gnomAD): Loss-of-function variants: 6 observed, 35.98 expected, observed/expected ratio (o/e) 0.17, 90% interval 0.09 to 0.33. The upper end of that interval is the gene's LOEUF score, 0.33, which puts it in group 1 of 6, group 1 being the genes least tolerant of losing a copy. Missense variants: 434 observed, 725.73 expected, observed/expected ratio (o/e) 0.6, 90% interval 0.55 to 0.65. Synonymous variants: 338 observed, 323.36 expected, observed/expected ratio (o/e) 1.05, 90% interval 0.96 to 1.14.
Homologues: Orthologues: chimpanzee NACC1 (100% identical), macaque NACC1 (99% identical), pig NACC1 (94% identical), dog NACC1 (94% identical), mouse Nacc1 (87% identical), rat Nacc1 (87% identical), guinea pig NACC1 (86% identical), tropical clawed frog nacc1 (74% identical), zebrafish nacc1b (73% identical), zebrafish nacc1a (72% identical). Paralogues in human: NACC2 (54% identical), ZBTB21 (19% identical), ZBTB33 (17% identical), ZBTB46 (16% identical), BCL6 (15% identical), ZBTB49 (14% identical), BCL6B (13% identical), ZBTB12 (13% identical), ZBTB14 (13% identical), ZBTB3 (13% identical), ZBTB7B (13% identical), ZBTB26 (12% identical), and 16 more.
Diseases named in the same sentence as NACC1 in open-access papers:
NACC1 is named in the same sentence as 62 diseases in open-access papers, as found by Europe PMC text mining. Sharing a sentence is not in itself a finding about the gene and the disease. The quoted sentences say what the papers report.
ovarian carcinoma (14 papers, 2013 to 2025). A malignant neoplasm originating from the surface ovarian epithelium. "Abnormal expression of NACC1 was shown to be linked to the poor prognostic features of many types of malignant tumors, such as ovarian cancer 28, 29, colorectal cancer 30, melanoma 31, 32, hepatocellular carcinoma 33 and other diseases." (PMID 39898241, 2025). "Upregulation of LINC00319 has carcinogenic effects and enhances the expression of nucleus accumbens associated 1 (NACC1) by inhibiting miR‐423‐5p, which then promotes ovarian cancer cells metastasis and proliferation." (PMID 33174687, 2020). "NACC1 was also identified as a cancer-associated BTB gene by serial analysis of gene expression in ovarian cancer cells." (PMID 29983869, 2018). "Furthermore, sEVs from human umbilical cord mesenchymal stem cells (MSCs) can regulate the expression of nucleus accumbens-associated protein 1 (NACC1) by transporting miR-18a-5p, which influences the Akt/mTOR pathway, thereby curbing ovarian cancer cell proliferation." (PMID 40008006, 2025). "The downregulation of LINC00319 was able to curtail the malignant activity of ovarian cancer cells by repressing the expression of NACC1 through miR-423-5p." (PMID 40999508, 2025). "In this study, a statistical difference in NACC1 expression was observed between all races in ovarian cancer." (PMID 39769395, 2024). "NACC1 has been indicated to contribute to tumor progression in different cancers, such as lung adenocarcinoma, mantle cell lymphoma, and ovarian cancer." (PMID 35034547, 2022). "Multiple evidence show that NACC1 is related to chemotherapeutic resistance and cancer recurrence, and affected overall survival and disease-free survival in ovarian cancer patients." (PMID 30248959, 2018). "In ovarian cancer, miR‐339 inhibited the tumor progress by directly regulating NACC1 and Bcl6 while miR‐339 regulated the metastasis of colorectal cancer via targeting PRL‐1.23, 24 LncRNA RP11‐81H3.2 might function as a ceRNA and sponge the miR‐339." (PMID 32052594, 2020). "Considering the TCGA database, there has been no comparative analysis of NACC1 expression between normal tissue and ovarian cancer." (PMID 39769395, 2024). "Importantly, we observed a strong correlation between the expression of NACC1 and BCL6 transcripts in the ovarian cancer cell lines tested (R2=0.7025; P=0.0185)." (PMID 32412910, 2020).
melanoma (7 papers, 2020 to 2024). A malignant, usually aggressive tumor composed of atypical, neoplastic melanocytes. "To do so, we established B16F10 melanoma cells deficient in either NACC1 or FKBP10 and then injected them into immune-competent or immune-incompetent mice." (PMID 37406115, 2023). "NACC1 was overexpressed in four melanoma cell lines compared with primary cultures of normal human epidermal melanocytes, and NACC1 knockdown significantly reduced the migratory activity of all melanoma cell lines." (PMID 39769395, 2024). "LINC00963 was reported to promote melanoma malignant progression by elevating expression of NACC1 through inhibiting miR-608." (PMID 35262384, 2022). "Notably, patients whose melanoma specimens showed high NACC1 and FKBP10 expression exhibited the worst overall survival, and those specimens also exhibited the highest NR2F6 expression relative to specimens expressing low NACC1 and FKBP10." (PMID 37406115, 2023). "Inhibition of NR2F6 expression by either shRNA KD or CRISPR-mediated KO inhibited melanoma growth in immune-competent but not immune-incompetent mice, an outcome phenocopied by NACC1 and FKBP10 loss." (PMID 37406115, 2023). "Interestingly, in melanoma, LINC00963 can also interact with miR-608 and further elevate nucleus accumbens associated 1 (NACC1) expression, facilitating cell proliferation, migration and invasion, similar to what is seen in AML." (PMID 35387124, 2022). "To further assess candidate NR2F6 effectors, we first validated NACC1, FKBP10, and CXCL10 expression levels in NR2F6 KD or KO mouse melanoma cells." (PMID 37406115, 2023). "Given the correlation in melanoma specimens, we set to correlate NR2F6, NACC1, and FKBP10 expression with patients’ overall survival and response to ICT in other cancer types." (PMID 37406115, 2023). "In the TCGA database, there has been no comparative analysis of NACC1 expression between normal tissue and melanoma, likely due to the lack of a comparison group." (PMID 39769395, 2024). "Important corroboration of our findings, tumor-intrinsic NR2F6, came from independent scRNA-seq analysis of human melanoma specimens: NR2F6, NACC1, and FKBP10 expression in malignant melanoma cells was significantly higher in samples from patients that are nonresponsive to anti–PD-1–based ICT." (PMID 37406115, 2023). "S5, M and N), suggesting that NACC1 regulation by NR2F6 is conserved in mouse and human melanoma." (PMID 37406115, 2023). "Unlike NACC1, FKBP10 expression was not affected by NR2F6 loss in human melanoma cells." (PMID 37406115, 2023). "Notably, analysis of melanoma patient data provided important support for our findings, revealing higher expression of NR2F6/NACC1/FKBP10 in nonresponders to ICT." (PMID 37406115, 2023).
epilepsy (5 papers, 2022 to 2024). A brain disorder characterized by episodes of abnormally increased neuronal discharge resulting in transient episodes of sensory or motor neurological dysfunction, or psychic dysfunction. "Following an analysis of the clinical manifestations, imaging assessments, and genetic screening, the patient was diagnosed with intellectual disability and profound developmental delay with epilepsy harboring a novel de novo NACC1 variant." (PMID 39421062, 2024). "The patient was diagnosed with intellectual disability and profound developmental delay with epilepsy harboring a novel de novo NACC1 variant." (PMID 39421062, 2024). "A recurrent de novo variant (c.892C>T) in NACC1 causes a neurodevelopmental disorder with epilepsy, cataracts, feeding difficulties, and delayed brain myelination (NECFM)." (PMID 37667351, 2023). "Recently, a de novo autosomal dominant mutation in NACC1 was identified (NM_052876.3: c.892C > T, NP_443108.1; p.Arg298Trp), associated with severe neurological symptoms including intellectual disability, microcephaly, and epilepsy." (PMID 37533751, 2023). "Patients suffering from Neurodevelopmental disorder with Epilepsy, Cataracts, Feeding difficulties, and delayed brain Myelination (NECFM, ORPHA: 500545) have a de novo heterozygous mutation (c.892C > T) in the NACC1 gene." (PMID 37160609, 2023). "Thus, the prevalence of epilepsy in patients expressing NACC1-R298W raises the possibility that aberrant regulation of GluK2A may play a role in the patients’ symptoms." (PMID 37533751, 2023).
Intellectual disability (4 papers, 2019 to 2024). "Variants in NACC1, particularly the novel de novo c.913A>G variant, lead to severe neurodevelopmental disorders and intellectual disability." (PMID 39421062, 2024). "This work provides the first insights into the functional impact of a de novo mutation in NACC1 identified in patients with intellectual disability." (PMID 37533751, 2023). "As intellectual disability is associated with disruption of synaptic transmission, we examined excitatory synaptic function in neurons expressing Nacc1-R284W, the mouse equivalent of NACC1-R298W." (PMID 37533751, 2023). "A de novo heterozygous c.892C>T (p.Arg298Trp) variant in the NACC1 may define a syndrome characterized by intellectual disability, infantile epilepsy, congenital cataract, and feeding difficulties." (PMID 34869110, 2021).
breast carcinoma (3 papers, 2023 to 2024). "Nucleus accumbens-associated protein-1 (NACC-1) is a transcriptional regulator implicated in the induction of tumorigenesis in ovarian and breast cancers." (PMID 37111734, 2023). "In the TCGA database, two correlation analyses were performed for the comparison of the expression levels of NACC1 between breast cancer types." (PMID 39769395, 2024). "NACC1 expression was demonstrated in breast cancer patients of all races." (PMID 39769395, 2024).
cervical cancer (3 papers, 2016 to 2025). A primary or metastatic malignant neoplasm involving the cervix. "NACC1 is one of several putative target molecules of miR-331-3p, and is associated with cell proliferation in cancers such as prostate and cervical cancer." (PMID 30248959, 2018). "In fact, increased expression of NACC1 was found to be associated with disease aggressiveness, development of chemoresistance, and tumor recurrence in several types of human cancer, including ovarian, endometrial, and cervical carcinomas." (PMID 30248959, 2018). "Furthermore, high expression of NACC1 has been correlated with low overall survival rates of patients suffering from cervical cancer." (PMID 39898241, 2025). "NRP2 expression was the highest in SKG-II and significantly decreased by miR-331-3p overexpression in SKG-II, HeLa and HCS-2 cells but NACC1 was not changed by miR-331-3p overexpression in SKG-II cells (data not shown); therefore, NRP2 might act as a target of miR-331-3p in cervical cancer cells." (PMID 27548144, 2016).
colorectal cancer (3 papers, 2020 to 2022). A primary or metastatic malignant neoplasm that affects the colon or rectum. "Mechanically, we demonstrated that ATF3 promoted FOXP4-AS1 expression, which exacerbates colorectal cancer progression via the miR-423-5p/NACC1 axis." (PMID 35034547, 2022).
infantile epilepsy (3 papers, 2017 to 2022). "From the WES data of a patient in the UDN with a sporadic phenotype of infantile epilepsy, cataracts, and developmental delay, the Duke Clinical Site identified a de novo missense variant in the nucleus accumbens associated 1 (NACC1) gene as one of several candidates for the child’s disorder." (PMID 28874452, 2017). "De novo mutations in NACC1 and disruption in EPM2A gene can lead to cerebral atrophy and infantile epilepsy." (PMID 36077118, 2022).
pancreatic cancer (3 papers, 2021 to 2024). "qRT-PCR showed that only NACC1 expression was negatively regulated by miR-600 mimics or inhibitors consistently in pancreatic cancer cell lines." (PMID 34416910, 2021). "In pancreatic cancer (PAAD), the RNA-binding protein FUS (FUS)-induced circular RNA (circRNA), circRHOBTB3, has been shown to aberrantly inhibit NACC1/Akt/mTOR signaling." (PMID 39769395, 2024).
prostate carcinoma (3 papers, 2016 to 2023). A carcinoma that arises from epithelial cells of the prostate gland. "We have previously reported that syndecan-1 (CD138) up-regulates miR-331-3p expression by directly targeting neuropilin 2 (NRP2) and nucleus accumbens-associated protein 1 (NACC1) to mediate the EMT in prostate cancer cells." (PMID 27548144, 2016). "We have previously reported that syndecan-1 (CD138) up-regulates miR-331-3p expression by directly targeting neuropilin 2 (NRP2) and NACC1 to mediate the EMT in prostate cancer cells." (PMID 30248959, 2018).
bladder tumor (2 papers, 2018 to 2024). "NACC1 expression was assessed in UC derived from a transurethral resection of a bladder tumor (TUR-Bt)." (PMID 39769395, 2024). "Furthermore, quantitative reverse transcription polymerase chain reaction and immunostaining were performed to evaluate the expression of NACC1 in UC derived from transurethral resection of bladder tumor (TUR-Bt) specimens." (PMID 30248959, 2018).
Dystonia (2 papers, 2022 to 2024). An abnormally increased muscular tone that causes fixed abnormal postures. "The phenotype of the patients with the recurrent NACC1 missense variant has neurological features, such as dystonia, that may overlap with those observed in primary mitochondrial disorders." (PMID 38698576, 2024).
esophageal cancer (2 papers, 2023 to 2024). A primary or metastatic malignant neoplasm involving the esophagus. "When we looked into the tumor grade, the expression levels of NACC1 differed in esophageal carcinoma for G1 vs. G3, N vs. G1, N vs. G2, and N vs. G3." (PMID 39769395, 2024).
lung adenocarcinoma (2 papers, 2022). A carcinoma that arises from the lung and is characterized by the presence of malignant glandular epithelial cells. "Another study revealed that hsa_circ_0001588 upregulated the expression of NACC1 by combining with miR-524-3p to promote the proliferation, migration, and invasion of lung adenocarcinoma cells." (PMID 36439541, 2022).
lung cancer (2 papers, 2021 to 2023). A malignant neoplasm involving the lung. "circ_0001588 induces the progression of lung cancer by modulating miR-524-3p and NACC1 signaling." (PMID 34722778, 2021).
ovarian serous carcinoma (2 papers, 2014 to 2022). "Amplification of the gene encoding Nac1, NACC1, has been implicated as one of the top potential ‘drivers’ in human ovarian serous carcinoma, and high levels of Nac1 may also be relevant in ovarian clear cell carcinoma and in some cervical and uterine cancers." (PMID 24702277, 2014). "Few genomic alterations has ever been reported in NACC1, but it is activated in ovarian serous carcinomas and influences cell apoptosis, senescence, and cytokinesis in cancer cells." (PMID 35650238, 2022).
pancreatic ductal adenocarcinoma (2 papers, 2021 to 2022). An infiltrating adenocarcinoma that arises from the epithelial cells of the pancreas. "In addition, circRHOBTB3 could regulate autophagy via miR-600/NACC1 axis in pancreatic ductal carcinoma." (PMID 35148775, 2022).
urothelial carcinoma (2 papers, 2018 to 2021). A malignant neoplasm derived from the transitional epithelium of the urinary tract (urinary bladder, ureter, urethra, or renal pelvis). "Functional experiments involving miR-331-3p and its target molecule NACC1 were conducted using the urothelial carcinoma (UC) cell lines, T24, UMUC6, and KU7." (PMID 30248959, 2018).
virus infection (2 papers, 2015 to 2023). "For example, endogenous NACC1 appeared more stable during mSLS4 than wt virus infection whereas MORC3 was equally sensitive to the two viruses." (PMID 26200910, 2015).
Autoimmunity (1 paper, 2023). The occurrence of an immune reaction against the organism's own cells or tissues. "PIM deficiency further promoted expression of the nucleus accumbens-associated protein 1 (NACC1), a TF that is upregulated under pro-inflammatory conditions and promotes autoimmunity by destabilizing FOXP3 expression and suppressing Treg-mediated tolerance." (PMID 38039135, 2023).
carcinoma in situ (1 paper, 2018). "Interestingly, NACC1 was expressed at significantly higher levels in low-grade, non-invasive UC and high-grade carcinoma in situ (pTis), compared with invasive UC (pT1 vs. pT2; p = 0.003)." (PMID 30248959, 2018).
Cerebral ischemia (1 paper, 2025). Restriction of arterial blood supply to the brain associated with insufficient oxygenation to support the metabolic requirements of the tissue. "Moreover, miR-361-3p alleviates cerebral ischemia–reperfusion injury by targeting NACC1 through the PINK1/Parkin pathway." (PMID 41446787, 2025).
Cirrhosis (1 paper, 2024). A chronic disorder of the liver in which liver tissue becomes scarred and is partially replaced by regenerative nodules and fibrotic tissue resulting in loss of liver function. "Our study aimed to elucidate the molecular mechanisms underlying NAC1 (nucleus accumbens associated 1) transcriptional regulation of LDHA and its role in HBV immune evasion, thus contributing to the development of cirrhosis and hepatocellular carcinoma (HCC)." (PMID 38704368, 2024).
colon carcinoma (1 paper, 2024). "Therefore, this fact confirms the significant role of NACC1 in the development of colon cancer." (PMID 39769395, 2024).
endometrial cancer (1 paper, 2023). Primary or metastatic malignant neoplasm involving the endometrium (mucous membrane that lines the endometrial cavity). "However, there have been no reports on the involvement of PRMT2, NEK6, NACC1, ATP2A2, and TM4SF19 in endometrial cancer." (PMID 37780629, 2023).
Failure to thrive (1 paper, 2023). Failure to thrive (FTT) refers to a child whose physical growth is substantially below the norm. "Furthermore, consistent with the patient hypotonia and failure to thrive, the Nacc1 KO mice showed motor impairment and perturbed growth." (PMID 37160609, 2023).
generalized dystonia (1 paper, 2022). "In eight patients with generalized dystonia from infancy, the mutation of PIGA, TCF4, CHRNG, SLC16A2, KCNQ2, NACC1, CTNNB1, or ARSA gene were found to be causative." (PMID 35719373, 2022).
liver cancer (1 paper, 2014). An epithelial or non-epithelial malignant neoplasm that arises from the liver. "RANBP10, IRF1 and ZNF395 were found to be down-regulated in liver cancer tissues, while the expression levels of NACC1 and MLST8 remained unchanged." (PMID 24599008, 2014).